BRCA1 (BRCA1 DNA repair associated)
Diseases named in the same sentence as BRCA1 in open-access papers (continued):
Sharing a sentence is not in itself a finding about the gene and the disease.
breast cancer (continued). "The time elapsed since RRSO and age at RRSO consistently predicted psychological symptoms in women with BRCA1, those with no history of breast cancer, and those who were premenopausal at RRSO." (PMID 39201170, 2024). "BRCA1 has previously been reported to interact with MSN/RDX through its BRCT domain, an interaction that localises the protein to the leading edges and focal adhesion sites in breast cancer cells." (PMID 39009827, 2024). "Decreased BRCA1 and USP4 was observed in 59% (134 of 226) and 63% (143 of 226) of breast cancer respectively, whereas only 10% (23 of 226) and 8% (18 of 226) exhibited high expression, suggesting that both BRCA1 and USP4 are downregulated in human breast cancers." (PMID 38734703, 2024). "There are no studies on the influence of HRT on breast cancer recurrence in BRCA1/2-pV carriers without RRSO." (PMID 39259360, 2024). "Specifically, deleting BRCA1 in murine luminal cells, but not basal cells, generates tumors resembling human basal-like breast cancers." (PMID 37832945, 2024). "Interestingly, BRCA1-type breast cancer lines all clustered with the basal subtype, whereas BRCA2-type breast cancer lines represented a variety of subtypes." (PMID 39485057, 2024). "We next examined the capacity of the validated drugs to reduce BRCA1 expression in MDA-MB-231 cells, a triple-negative breast tumor cell line that is representative of BRCA1-expressing basal-like breast cancer." (PMID 38993666, 2024). "SIRT4 might affect breast cancer CSCs by altering SIRT1 expression, targeting H4K16Ac and BRCA1, and affecting the process of autophagy." (PMID 38397988, 2024). "Given the effect of combined deletion of Wwox and Brca1 on mammary tumor formation and the known effect of WWOX/BRCA1 interaction on DNA repair pathway choice in vitro, we next set to examine which DSB repair pathway is favored in tumors of K14-Cre;Brca1fl/fl;Wwoxfl/fl mice." (PMID 38499540, 2024). "Independent of PRC2, EZH2 regulates the shuttling of BRCA1 protein from the nucleus to the cytoplasm in basal-like breast cancer cells." (PMID 39682099, 2024). "Notably, the CF methylation carriers expressed significantly higher levels of the two genes (p = 0.0001 for BRCA1 and 0.015 for MGMT) than the breast cancer patients." (PMID 38542081, 2024). "Here we report on long-term breast cancer incidence and cumulative breast cancer mortality of a cohort of women with a BRCA1 or BRCA2 sequence variation who did or did not undergo MRI surveillance." (PMID 38421676, 2024). "Additionally, methyl-binding domain protein 2’s variable binding to the BRCA1 promoter is increased by resveratrol, preventing gene suppression in MCF-7ER-positive breast cancer cells." (PMID 39846533, 2024). "Height was a risk factor for premenopausal breast cancer in BRCA2 variant carriers, but not BRCA1 carriers." (PMID 37340476, 2023). "Among breast cancer patients the most prevalent occur in BRCA2, CHEK2, BRCA1 and ATM." (PMID 37790698, 2023). "It has been demonstrated that some surgeons have performed bilateral breast mastectomies on patients with unilateral breast cancer with VUS in BRCA1 and BRCA2 without consulting a medical geneticist or a genetic counselor." (PMID 38028588, 2023). "in particular, breastfeeding showed a positive impact on certain types of breast cancer, including BRCA-1, HER2+, and receptor-negative breast cancers." (PMID 37750138, 2023).
breast cancer (continued). "Another possible explanation for not finding a risk-reducing effect of RRSO on breast cancer risk is that the optimal timing of RRSO to prevent tubal/ovarian cancer is between 35 and 40 years for BRCA1 GPV carriers and between 40 and 45 years for BRCA2 GPV." (PMID 37046756, 2023). "iNOS/NOS2 axis promotes breast cancer progression through regulating HER2, BRCA1, and BRCA2." (PMID 37795447, 2023). "Although HER2+ breast cancers that are negative for oestrogen and progesterone receptors are more likely to be BRCA1 driven than those that are oestrogen overexpressed." (PMID 37592173, 2023). "For example, screening for the BRCA-1 and BRCA-2 genes in breast cancer could have important implications for the early warning of breast cancer." (PMID 37181711, 2023). "The patient reported a positive family history (sister with breast cancer at the age of 42 years) and was one of the 47 women who had undergone genetic counselling and germline testing for large BRCA1/2 rearrangements, which yielded negative results." (PMID 37179432, 2023). "This challenges clinical genetic counselling of families with a strong history of breast cancer without identified germline mutations in BRCA1 and BRCA2 (hereafter referred to as non-BRCA1/BRCA2 high-risk families)." (PMID 37316882, 2023). "Although the study involved a large cohort of unselected patients with breast cancer, the BRCA1/2 carrier sample size was not sufficiently large, and some types of cancer were rare after stratification by gender and gene type." (PMID 36861435, 2023). "We report the genomic profile of BRCA1/2-related breast cancer, and provide evidence that non-BRCA genetic/genomic events did not appear to impact the efficacy of talazoparib." (PMID 37803017, 2023). "The incidences of breast cancer in female relatives of BRCA1 carriers, BRCA2 carriers, and non-carriers were 33.0%, 32.2%, and 7.7%, respectively." (PMID 36861435, 2023). "Thus, considering our in vitro and in vivo findings, BRCA1- and BRCA2-based gene therapy using CA NPs as delivery vector reveals a highly promising approach to treating breast cancer." (PMID 36631481, 2023). "While early age at diagnosis was strongly associated with BRCA1 and modestly with BRCA2, it was associated with only a very modestly (ATM and CHEK2) or no (PALB2) increased risk of carrying a PV in non-BRCA1/2 breast cancer-associated genes." (PMID 37084156, 2023). "These 14 samples included one BRCA1-defective sample (sc5rJUQ033), which we assumed to be HRD, and one Stage II Luminal A sample (sc5rJUQ064) which we assumed to be HR-proficient, given the characterisation of this type of breast cancer as slow-proliferating." (PMID 37919776, 2023). "Given the high proportion of triple-negative breast cancer in BLBC and the common feature of BRCA1-defective breast cancer and BLBC, perhaps for the treatment modalities of CNC, we can attempt to use targeted therapy for BRCA1." (PMID 37114130, 2023). "Supporting these, overexpression of PDE4D in ER+ breast cancer cells almost completely blocked SOC-induced mitochondrial ROS generation and rescued G1/S progression and cell viability by preventing DNA damage and BRCAness in the BRCA1/2 wt cells." (PMID 37914699, 2023). "Unlike BRCA1-associated cancers, BRCA2 tumours often express estrogen and progesterone receptors with similar features as sporadic breast cancers." (PMID 36980802, 2023). "The cell of origin (COO) in BRCA1 mutant breast cancer is not clear, and the process of BRCA1 mutant breast cancer development has not been fully elucidated." (PMID 37612741, 2023).
breast cancer (continued). "Previous researchers detected only 24 mitochondrial variants predicted to be deleterious by SIFT and probably damaging by PolyPhen2 in a cohort of 436 French Nationals with familial breast cancer but testing negative for BRCA1 and BRCA2." (PMID 36758048, 2023). "EEPD1was thought to be responsible for mitotic catastrophe in breast cancer cells (BRCA1 mutant) in the absence of RAD52, suggesting its critical role in cancer cell survival." (PMID 37818043, 2023). "The question remains open as to whether our findings are restricted to BRCA1 and BRCA2 or if they represent a small part of a global reduction of circRNAs in breast cancer." (PMID 37046838, 2023). "In oncologic BRCA1/2 patients, B/M are similarly elevated compared with breast cancer patients, but without statistical significance." (PMID 37623237, 2023). "BRCA1 has a relationship within breast cancer and OC and cell cycle is very important to any types of cells, our study revealed a previous unprecedented mechanism that ZFP57 accelerates cell cycle by regulating BRCA1 and G1 checkpoint." (PMID 37497403, 2023). "In recent studies, MUTYH-monoallelic germline variants have been reported in patients with early-onset or familial breast cancer and in BRCA1/2 negative breast cancer patients." (PMID 37656691, 2023). "Taken together, these findings reveal an allelic concordance between BRCA1 methylation in WBC and matched cancer or benign tissue in the breast cancer samples, indicating that the methylated tumors have arisen from methylated normal cells in the affected mosaic individuals." (PMID 38053165, 2023). "We hypothesized that due to their histological differences, BRCA1 and BRCA2 breast cancers demonstrate different imaging characteristics on ultrasound." (PMID 36905492, 2023). "Although BRCA1 mutant breast cancers are usually Her2 negative, a significant percentage of Her2 positive tumors also lose their expression of BRCA1." (PMID 37627161, 2023). "The data show that there is a correlation between BRCA1 and BRIP1 in breast cancer patients." (PMID 36873936, 2023). "In patients who are found not to carry a founder mutation, we perform full sequencing using gene panels including BRCA1, BRCA2, CHEK2, and PALB2 in breast cancer cases with familial clustering of this cancer and/or in patients with early onset disease (diagnosed at age 45 or below)." (PMID 37510234, 2023). "BRCA1 mutations are linked preferentially to the triple negative form of BC (estrogen receptor negative, progesterone receptor negative, and HER2 negative, TNBC), whereas BRCA2-associated breast cancers are generally estrogen receptor-positive, and phenotypically different (mostly luminal-like BC)." (PMID 36902416, 2023). "Pathologic and ultrasound features of BRCA1 and BRCA2 breast cancers were previously assessed, although several essential variables, such as vascularity or elasticity, remain unknown." (PMID 36905492, 2023). "Taken together, these results demonstrate that SIN1 plays an important role in breast cancer, in particular for patients lacking functional BRCA1." (PMID 37877351, 2023). "In a group of patients with hereditary breast cancer, PIK3CA mutations were associated with BRCA2 but not BRCA1 mutations, and with luminal-type breast cancer." (PMID 37803017, 2023). "In support of this notion, the selective removal of the Brca1 gene from K14 and K6a-positive basal epithelial cells is not sufficient to trigger the development of mammary cancer." (PMID 38067308, 2023). "We uncovered that BRCA1 binds to the GATA3 binding sites in the promoter of PDGFRβ to repress its transcription and that depletion of Brca1 stimulates the expression of PDGFRβ activating the PDGFRβ-PKCα-FRA1 pathway to induce EMT and drive CSC function in breast cancer." (PMID 37353480, 2023).
breast cancer (continued). "Poly(adenosine diphosphate-ribose) polymerase inhibitors (PARPi) improve progression free survival among patients with HER2 negative (HER2-ve) advanced breast cancer (ABC) and a BRCA1 or BRCA2 mutation compared to chemotherapy (CT)." (PMID 38414929, 2023). "For instance, platin-based treatment irrespective of BRCA1/2 status has been standard for groups of the ovarian and pancreatic cancer patients, while traditionally not for the breast cancer patients." (PMID 36883553, 2023). "In the cohort of women with BRCA1/2 mutations, short-term HRT following RRSO did not alter the significant reduction in breast cancer risk associated with RRSO during the available follow-up period." (PMID 36614207, 2023). "In addition, mis-splicing of tumor suppressor genes, such as BRCA1, PTEN in breast cancer, and KRAS in lung cancer, are also reported to promote tumor initiation." (PMID 37635865, 2023). "Neither synchronous nor metachronous breast cancer is associated with strong genetic determinants, and only 5% of patients with BBC carry BRCA1 or BRCA2 mutations." (PMID 36879128, 2023). "Similarly, in breast cancer, the deletion of specific PPARγ in CAA downregulates BRCA1 expression and accelerates tumor formation and progression." (PMID 37251321, 2023). "Further, in BRCA1 mutation carriers, HRT use without RRBSO was also shown to be associated with a reduced risk of breast cancer (HR 0.29 [95% CI 0.13, 0.69])." (PMID 36765666, 2023). "UBE2N interacts with BRCA1, and its expression serves as a potential biomarker of response to poly(ADP-ribose) polymerase (PARP) inhibitors and other DNA-repair-targeted therapies in breast cancer." (PMID 37869102, 2023). "We applied a previously developed PRS to 406 women with germline BRCA1 pathogenic variants and found that the PRS accurately predicted breast cancer risk, but not ovarian cancer risk." (PMID 37296919, 2023). "In this cohort of 1312 women with a BRCA1/2 GPV, after RRSO the breast cancer risk did not decrease for both BRCA1 (HR: 1.29, 95% CI: 0.81–2.05) and BRCA2 GPV carriers (HR: 1.13, 95% CI: 0.62–2.06) compared to pre-RRSO." (PMID 37046756, 2023). "Moreover, there are other isoforms have been reported to promote tumor metastasis, including KLF6-SV1, and BRCA1-IRIS in breast cancer." (PMID 37635865, 2023). "Due to few cases, the present study did not evaluate male breast cancer separately, but a validation study focused on this group of patients has previously demonstrated acceptable performance of the model for BRCA1 and BRCA237." (PMID 37237042, 2023). "BRCA1 and ZBRK1 then form a complex that inhibits breast cancer cell proliferation." (PMID 38049396, 2023). "Specifically, BRCA1 germline mutations predispose to the occurrence of triple-negative breast cancer (TNBC), an aggressive subtype of breast cancer (BC) that is negative for the expression of the hormone receptors (HR), ERα and PR, and HER2." (PMID 37373065, 2023). "In particular, a link between the expression of BRCA1 and RAD51 and the development of mammary tumors was hypothesized in dogs." (PMID 36288156, 2022). "Of note, the prevalence of BRCA1/2 germline LGR in other cancers, except for ovarian and breast cancers, might be underestimated because a few cases were screened only with tissue specimens." (PMID 36147908, 2022). "Two previous studies used Co-IP to demonstrate that BRCA1 interacts with PR in the absence of progestins in T47D breast cancer cells." (PMID 36076907, 2022). "For example, breast cancer monitoring is not clinically indicated for an adolescent < 18 years receiving a P/LP BRCA1 result." (PMID 36422086, 2022). "In addition to breast cancer and ovarian cancer, there are also several clinical trials on PARP inhibitors for BRCA1/2- or ATM- mutant patients with prostate cancer or cervical cancer [NCT04641728]." (PMID 35055413, 2022). "If BRCA1 or BRCA2 is damaged by a BRCA mutation, damaged DNA is not repaired properly, and this increases the risk for breast cancer." (PMID 35837379, 2022).
breast cancer (continued). "In our material in BRCA2 carriers bilateral breast cancer was more common compared to BRCA1 carriers, but this result was not significant." (PMID 35469032, 2022). "Most carriers of BRCA1 and BRCA2 with luminal breast cancer in stage I benefited from RRBM-RRBSO." (PMID 36580360, 2022). "Because PARPi agents improve progression-free survival with ER+ gBRCA breast cancer in most clinical trials, breast cancer should be considered, regardless of ER status, for BRCA1/2 screening for therapeutic purposes." (PMID 35805038, 2022). "In our first pathology update of the Manchester Scoring system, 11% of familial breast cancers that tested negative for BRCA1/2 were lobular, but lobular cancer was present in only 1.6% of index BRCA1 cases." (PMID 33763779, 2022). "RAD6B is overexpressed in TNBC cell lines and clinical tumors independent of their BRCA1 status, and its overexpression correlates with breast cancer progression and chemoresistance." (PMID 36258187, 2022). "Using two breast cancer cell lines, MCF-7 and MDA-MB 231, genistein influenced H3 and H4 histones on H3K27me3, H3K9me3, H3K4me3, H4K8ac, and H3K4ac marks, on six genes (EZH2, BRCA1, ERa, ERb, SRC3, and P300)." (PMID 35327559, 2022). "Highest pCR rates are achieved in patients with germline BRCA1-mutant breast cancer due to increased genomic instability, however, no overall survival benefit was observed." (PMID 35715861, 2022). "It means that often young women affected with BRCA1/2 positive breast cancer have not finished or even not started their childbearing before the onset of the disease." (PMID 35062994, 2022). "In the analysis of human database, we found that S100A9 expression level was positively correlated with human breast cancer development stages and Pearson correlation analysis revealed a negative correlation between BRCA1 and S100A9 in breast cancer patients." (PMID 35304461, 2022). "As for the GnRH pathway, while there is not a direct link to BRCA1, GnRH agonists have been shown to be effective in the treatment of breast cancer." (PMID 35118379, 2022). "Mutations in BRCA1 and BRCA2, in addition to ERBB2, were also newly present in brain metastatic tumors and not detected in primary breast tumors in eight out of 22 breast cancer patients." (PMID 36507516, 2022). "BRCA2- related cancers, unlike BRCA1, frequently express estrogen and progesterone receptors and have many of the same features as sporadic breast cancer." (PMID 35409110, 2022). "Considering that PARP inhibitors can elicit cell death in BRCA1 or BRCA2 mutant breast cancer cells, we speculated that LCS-1 may induce cell death via degrading PARP and BRCA1." (PMID 35978820, 2022). "That is, 67.2% of the early-stage ER+ tamoxifen-treated breast cancer patients were free of DM during the 15 years of follow-up, regardless of their BRCA1 expression level." (PMID 34996912, 2022). "TBX2 amplification has been reported to be enriched in BRCA1 mutant breast cancers (which are predominantly ERα-negative) but the in vitro models we have used are predominantly ERα-positive." (PMID 35687133, 2022). "The combined BRCA1 and BRCA2 VUS rate in a cohort of 21,216 Chinese breast cancer cohort was 9.8%." (PMID 35641994, 2022). "The frequency of somatic BRCA1 and BRCA2 PV may be between 1 and 3% of patients in unselected breast cancer populations, including ER+/HER2- breast cancer patients and even higher in patients with ER+/HER2- mBC." (PMID 35158866, 2022).